PDE4B (phosphodiesterase 4B)
Diseases named in the same sentence as PDE4B in open-access papers (continued):
Sharing a sentence is not in itself a finding about the gene and the disease.
brain inflammation (1 paper, 2021). "Moreover, two research groups reported that PDE4B deficiency reduced lung injury and alcohol-induced brain inflammation in mice, respectively." (PMID 34977026, 2021).
breast tumors (1 paper, 2016). "The expression of PDE4B was significantly higher in basal-like breast tumors compared with other breast tumor types." (PMID 27901486, 2016).
chronic kidney disease (1 paper, 2026). Impairment of the renal function secondary to chronic kidney damage persisting for three or more months. "In chronic kidney disease, elevated levels of fibroblast growth factor 23 inhibited PDE4B expression in cardiomyocytes, further increasing sarcoplasmic reticulum Ca2+ leakage as well as promoting ventricular arrhythmias." (PMID 41602587, 2026).
coronary artery disease (1 paper, 2023). "Certainly, cardiac PDE4B expression was specifically upregulated in a mouse model of myocardial ischemia/reperfusion (MI/R) and in patients with coronary artery disease, in which PDE4B was localized in endothelial and myeloid cells." (PMID 38069339, 2023).
Cough (1 paper, 2024). A sudden, audible expulsion of air from the lungs through a partially closed glottis, preceded by inhalation. "The investigation revealed that AG NPP709 effectively inhibits tachykinin NK1, NK2, phosphodiesterase 4B (PDE4B), and adenosine A3 receptors, which are implicated in airway smooth muscle contraction, a key factor in cough pathogenesis." (PMID 39596310, 2024).
Cryptococcal meningitis (1 paper, 2026). Meningeal inflammation produced by cryptococcus neoformans, an encapsulated yeast that tends to infect individuals with acquired immunodeficiency syndrome and other immunocompromised states. "Overall, this study revealed that PDE4B functions as an important regulator of macrophage functional programming during infection and supports a macrophage-mediated dissemination mechanism contributing to brain invasion, and is a potential therapeutic target for cryptococcal meningitis." (PMID 41805786, 2026).
dystrophinopathy (1 paper, 2022). "Among these genes, Pde4b is reported to affect the severity of dystrophinopathy, and Kcnma1, and Hs6st3 play roles in myogenesis." (PMID 36123393, 2022).
esophageal cancer (1 paper, 2021). A primary or metastatic malignant neoplasm involving the esophagus. "Furthermore, treatment of immunodeficient mice bearing esophageal cancer xenografts (TE1 cell-derived) with alvespimycin hydrochloride (AH, an HSP90AA1 inhibitor) or ML-030 (a PDE4B inhibitor) remarkably suppressed tumor growth." (PMID 34294701, 2021).
frontotemporal dementia (1 paper, 2024). Frontotemporal dementia (FTD) comprises a group of neurodegenerative disorders, characterized by progressive changes in behavior, executive dysfunction and language impairment, as a result of degeneration of the medial prefrontal and frontoinsular cortices. "Rolipram suppresses tau phosphorylation in 11-month-old 3xTg-AD mice and in the rTg4510 mouse model of frontotemporal dementia at 3–4 months of age, but no work has been published on the effects of PDE4B subtype-specific inhibition on tau pathology." (PMID 38521860, 2024).
gastroesophageal reflux disease (1 paper, 2025). A chronic disorder characterized by reflux of the gastric and/or duodenal contents into the distal esophagus. "A large-scale genome-wide cross-trait (GWAS) identified PDE4B as a significant susceptibility locus shared between AD and gastroesophageal reflux disease." (PMID 40093898, 2025).
gastroparesis (1 paper, 2026). Paralysis of the muscles of the stomach wall resulting in delayed emptying of the gastric contents into the small intestine. "Roflumilast inhibited gastric transit more effectively than selective PDE4B inhibitors, but PDE4 inhibitor-induced gastroparesis wasn’t influenced by gene deletion of any one PDE4 subtype, illustrating that two or more PDE4 subtypes may be involved in this condition." (PMID 41602587, 2026).
glioblastoma (1 paper, 2021). The most malignant astrocytic tumor (WHO grade IV). "Furthermore, the expression of several PDEs is upregulated in glioblastoma cells, and the specific isoforms PDE1C, PDE4A, PDE4B, PDE4D and PDE5 have been suggested as therapeutic targets in glioblastoma." (PMID 34575827, 2021).
glioma (1 paper, 2021). A benign or malignant brain and spinal cord tumor that arises from glial cells (astrocytes, oligodendrocytes, ependymal cells). "For instance, PDE4A expression is elevated in central nervous system tumor cells, and PDE4B expression in increased in hematologic malignancies, whereas hypermethylation of PDE4C promoter sites was reported in high-grade glioma samples." (PMID 34066000, 2021). "PDE4 consists of four subtypes, PDE4A, PDE4B, PDE4C and PDE4D, and is involved in several human malignancies including prostate cancer, leukemia, colon cancer and glioma." (PMID 34066000, 2021).
Insulin resistance (1 paper, 2021). Increased resistance towards insulin, that is, diminished effectiveness of insulin in reducing blood glucose levels. "Collectively, we found that the genes SRR, PDE4B, and NFKB1A were directly and indirectly associated with insulin secretion, insulin resistance, and T2DM." (PMID 35046895, 2021). "It has been observed that PDE3A, PDE3B, PDE4B, PDE4D, and PDE8B in rat islets and in INS-1E cells activate multiple signal pathways critical for pancreatic beta cell function, and their abnormalities are associated with insulin resistance." (PMID 35046895, 2021).
Intellectual disability (1 paper, 2016). "We also determined the transcript levels of six candidate genes (DAB1, HOOK1, NFIA, DOCK7, DNAJC6 and PDE4B) for syndromic intellectual disability." (PMID 26997977, 2016). "Comparative deletion mapping showed that there are at least six candidate genes including, NFIA, HOOK1, DOCK7, DAB1, DNAJC6, and PDE4B, that could contribute to the syndromic or non-syndromic intellectual disability." (PMID 26997977, 2016). "We propose six candidate genes (DAB1, HOOK1, DOCK7, DNAJC6, PDE4B, and NFIA) for the clinical features such as intellectual disability and OCD observed in DGDP005, because each of these genes is involved directly or indirectly in neurological disorders." (PMID 26997977, 2016).
ischemia reperfusion injury (1 paper, 2025). Adverse functional, metabolic, or structural changes in ischemic tissues resulting from the restoration of blood flow to the tissue (reperfusion), including swelling; hemorrhage; necrosis; and damage from free radicals. "A recent study found that inflammatory reactions and microcirculatory disturbances associated with neutrophils that protect the heart from ischemia-reperfusion injury are mediated by PDE4B." (PMID 40231027, 2025).
keloid (1 paper, 2024). An irregularly shaped, elevated mark on the skin caused by deposits of excessive amounts of collagen during wound healing. "In our study, we observed that PDE4B was the most abundantly expressed isoform in the epidermis of hypertrophic scars and keloids, followed by PDE4D." (PMID 39223490, 2024). "The analysis of PDE4 subtypes showed PDE4B the most overexpressed in keratinocytes from hypertrophic scars and keloids followed by PDE4D expression and in a lesser extent by PDE4A and PDE4C." (PMID 39223490, 2024). "The study found increased levels of PDE4B (mRNA, protein) in keloids > HTS compared to healthy epidermis, as well as in TGFβ-stimulated 3D epidermis." (PMID 39223490, 2024). "Overall, the study supports the potential of PDE4 inhibitors, particularly PDE4B, in treating skin fibrosis, including keloids and HTS, shedding light on their functional role in this condition." (PMID 39223490, 2024). "In summary, this is the first report that characterize the role of PDE4 in the remodeled epidermis of pathological scars such as hypertrophic scar and keloids, showing that PDE4B inhibition could be an attractive target to attenuate the growth of the skin fibrotic lesion." (PMID 39223490, 2024).
multiple sclerosis (1 paper, 2024). A progressive autoimmune disorder affecting the central nervous system resulting in demyelination. "In a mouse model of multiple sclerosis, the PDE4B expression in antigen-presenting cells, such as phagocytes, was correlated with the disease severity." (PMID 38760316, 2024).
neuroblastoma (1 paper, 2022). Neuroblastoma (NB) is the most common solid, extracranial childhood tumor. "Although mechanism is unknown, the positive relationship between PDE4B knockdown and autophagy activation has been observed in SH-SY5Y neuroblastoma cells." (PMID 35941833, 2022).
opioid use disorder (1 paper, 2024). A substance-related disorder that involves the recurring use of opioids despite negative consequences. "Additionally, OPRM1 is targeted by naltrexone, which is FDA-approved for treating AUD and opioid use disorder, and as a combination drug, naltrexone-bupropion, for the treatment of obesity Importantly, both the PDE4B and OPRM1 loci exhibited concordant effects on AUD and BMI." (PMID 38746260, 2024).
osteosarcoma (1 paper, 2018). A usually aggressive malignant bone-forming mesenchymal neoplasm, predominantly affecting adolescents and young adults. "Previous studies indicate that dexamethasone decreases PDE4B expression in human pulmonary endothelial cells, airway epithelial cells, and osteosarcoma cells." (PMID 30413022, 2018). "Recent studies also showed that dexamethasone (Dex) decreases PDE4B expression in human pulmonary endothelial cells and osteosarcoma cells." (PMID 30413022, 2018). "Dex also suppressed the expression of PDE4B in human osteosarcoma cells." (PMID 30413022, 2018).
pulpitis (1 paper, 2025). Inflammation of the dental pulp. "For the phenotype Pulpal and apical diseases, two other loci in chromosomes 2 (near BCL11A) and 9 (near RMI1), and for the phenotype Pulpitis, three other loci in chromosomes 1 (near PDE4B), 9 (near NR4A3), and 17 (near VMP1 and TUBD1) were identified." (PMID 40701953, 2025).
silicosis (1 paper, 2025). Silicosis is a respiratory disease caused by breathing in (inhaling) silica dust. "Therefore, BI 1015550, as a PDE4B inhibitor, may exert its therapeutic effect by increasing cAMP levels in silicosis, and the same mechanism of action of BI 1015550 has been confirmed in SSc-ILD." (PMID 40142089, 2025).
steatosis (1 paper, 2022). Increased lipid within the cytoplasm of cells. "Our study showed that PDE4B inhibition by KVA-D88 markedly improved alcohol-induced steatosis in mice as indicated by Oil red O staining and hepatic TG content." (PMID 36145643, 2022).
cancer (20 papers, 2014 to 2024). A tumor composed of atypical neoplastic, often pleomorphic cells that invade other tissues. "Among all subtypes of PDE4, PDE4B is closely associated with cancer and has a major contribution to the role in hematological malignancies." (PMID 36278172, 2022). "DISC1 also regulates the cyclic adenosine monophosphate (cAMP) signaling pathway, which is associated closely with cancer pathogenesis and progression via binding and inhibition of phosphodiesterase 4B (PDE4B)." (PMID 31850367, 2019). "Dysregulation of PDE4B has been implicated in various cancers." (PMID 39075441, 2024). "Will frank human cancers show evidence for mutations in the PDE4B gene?" (PMID 30188895, 2018). "In addition, numerous studies have shown that PDE4B may be an oncogene in certain cancers and is closely associated with cancer pathogenesis through certain signaling pathways." (PMID 36278172, 2022). "In recent years, PDE4B selective-targeted therapies have shown promising therapeutic perspectives in anti-inflammation and anti-cancer." (PMID 36737782, 2023). "High expression levels of PDE4B promote the development of certain cancers and their subsequent invasion and metastasis." (PMID 36278172, 2022). "In this study, both cancer cell-derived exosomal miR-425-3p and PDE4B depletion similarly stimulated cAMP/PKA signalling and lipophagy in mature adipocyte, leading to adipocyte lipolysis." (PMID 35941833, 2022). "Accumulating evidence suggests that PDE4B plays an important role in the pathogenesis and clinical manifestations of cancer, including proliferation, migration, and drug resistance." (PMID 36278172, 2022). "Recent studies have identified phosphodiesterase 4B (PDE4B), a member of the phosphodiesterase (PDEs) protein family, as a major cyclic AMP (cAMP) metabolizing enzyme in inflammatory cells, and the therapeutic role of PDE4B as chronic inflammation, cancer." (PMID 36278172, 2022). "Recent studies have shown that PDE4B expression is elevated at the transcriptional as well as the translational level in various cancers." (PMID 36278172, 2022). "Further studies revealed that PDE4B mostly regulates the development of various cancers through the regulation of cAMP." (PMID 36278172, 2022). "Studies have shown that the PKA signaling pathway was a key mediator of cell proliferation and differentiation in various normal and cancer cells, and oxidative stress in tumor cells inhibited PDE4B expression and activated PKA path." (PMID 36278172, 2022). "There is also evidence that CMPK2 and PDE4B, which are immune checkpoint proteins in cancers, inhibit cell proliferation and induce apoptosis." (PMID 35957812, 2022). "The dysregulation of PDE4B is involved in a wide range of diseases progression, including Parkinson’s disease, depression, asthma, chronic obtrusive pulmonary disease, and cancer." (PMID 34977026, 2021). "Considering the specific gain of PDE4B SEs, we tested the effect of PDE4B inhibition in cancer metastasis." (PMID 34294701, 2021). "Functional studies demonstrated that ectopic expression of PDE4B promoted UBC cells proliferation, migration and invasion, whereas PDE4B depletion suppressed cancer cell aggressiveness." (PMID 34977026, 2021). "The expression of PDE4B varied among different cancer type and its prognostic significance remains controversial in cancer." (PMID 33585210, 2020). "Advancements in PDE4B selective-targeted therapies have shown promise in recent years for the treatment of inflammation, chronic obstructive pulmonary disorders, cancers, and myocardium contractility disorder." (PMID 25853062, 2014). "Numerous studies have shown that PDE4B played an important role in cancer progression." (PMID 36278172, 2022).
cancer (continued). "Overall, PDE4B is involved in the regulation of cellular signaling pathways and plays an important role in the development and clinical manifestations of inflammation as well as inflammation-induced cancer in multiple organs, suggesting PDE4B as a potential target for clinical therapy." (PMID 36278172, 2022). "However, more studies are required to figure out the crosstalk between PDE4B and Akt signalling pathways, as well as their contribution to lipolysis and adipocyte browning in cancer cachexia." (PMID 35941833, 2022). "In line with this, overexpression of PDE4B markedly enhanced cancer cells invasiveness." (PMID 34977026, 2021). "In addition, PDE4B is involved in the regulation of multiple signaling pathways in cancer cells." (PMID 36278172, 2022). "The expression levels of PDE4A, PDE4B and PDE4D were down-regulated in THCA patients at different cancer stages, while the expression level of PDE4C was significantly up-regulated." (PMID 38514754, 2024). "Therefore, it is expected that PDE4B may be a potential target for cancer therapy." (PMID 36278172, 2022). "Next, functional studies and bioinformatics analysis were carried out to define the role of PDE4B in EMT of UBC cells and cancer aggressiveness." (PMID 34977026, 2021). "Results: 239 genes were identified for further survival analysis, 5 of which were overlapping genes across at least five cancer types, including RHEBL1, PDE4B, ANKRD55, EPHB2, and GIMAP7." (PMID 34262492, 2021). "Using online algorithms, we were able to predict potential miR-361 target genes involved in cancer metastasis, such as MEF2D, ROCK1 and WNT7A, and the tumor microenvironment, including KPNA4, PDE4B and VEGF-A." (PMID 31287002, 2019). "PDE4B and PDE4D have recently been reported as oncogenes in various human cancers." (PMID 39202484, 2024). "Mechanistically, macrophage PDE4B might contribute to reprogram TAM phenotype towards a pro-inflammatory state, offering therapeutic avenues for cancer intervention." (PMID 39075441, 2024). "But the research of PDE4 inhibitors in cancer mainly surround PDE4A, PDE4B, and PDE4D28." (PMID 38514754, 2024). "Besides, we also observed that higher expression of PDE4B was specifically in basal/squamous subtype, which was the UBC subtypes with high malignant tumor grade and strong metastasis." (PMID 34977026, 2021). "Dysregulation of PDE4B has been reported in a variety of cancers, but its clinical significance has not yet been elucidated." (PMID 34977026, 2021). "Although compounds 48b, 48d, and 48e were identified as potent PDE4B inhibitors, they showed no cytotoxic activity towards the tested cancer cell lines." (PMID 25853062, 2014). "At present, there are no FDA-approved cancer treatments that target PDE4B, PDE4D, or SFRP5." (PMID 39202484, 2024).